PRMT5 (protein arginine methyltransferase 5)
Diseases named in the same sentence as PRMT5 in open-access papers (continued):
Sharing a sentence is not in itself a finding about the gene and the disease.
tumor (continued). "PRMT5 knockdown inhibits cyclin D1-dependent cell transformation causing death of tumour cells." (PMID 29946150, 2018). "The overexpression of PRMT5 was associated with tumour cell growth." (PMID 27860244, 2017). "Interestingly, nuclear PRMT5 expression was directly associated with high IL-6 expression in the primary tumor samples (p < 0.001)." (PMID 28107179, 2017). "Moreover, we linked coronin 2A to MAPK14 and PRMT5 signalling pathways involved in tumour progression." (PMID 26373535, 2015). "By investigating the interplay between PRMT5-mediated histone modifications and alternative splicing in the context of hypoxia, we aimed to unravel the complexities associated with epigenetics-mediated regulation of alternative splicing under hypoxia in promoting tumor progression." (PMID 41150697, 2025). "With respect to PRMT5, overexpression has been linked with multiple hematopoietic and solid cancers, and several selective PRMT5 inhibitors have recently been studied in Phase 1/2 trials, particularly to target tumor dependencies on PRMT5 functioning as a splicing regulator." (PMID 37237172, 2023). "To establish whether the observed tumor cell death was associated with selective inhibition of PRMT5’s symmetric dimethyl transferase activity, we performed western blot analysis of protein extracts using anti-sera specific for symmetric and asymmetric dimethyl arginine." (PMID 33989303, 2021). "Interestingly, we found that PRMT5 deficiency in tumor cells decreased PD-L1 expression, which could promote antitumor immunity." (PMID 34522232, 2021). "Together, these potentially serve to facilitate the tumor-associated functions exerted by this PKCι-mediated PRMT5-dependent NF-κB activation, including the enhanced proliferation, anchorage-independent growth, and migration associated with PRMT5 overexpression." (PMID 32456215, 2020). "Loss of MTAP leads to the accumulation of 5'-methylthioadenosine (MTA), which sensitizes tumor cells to inhibition of protein arginine methyltransferase 5 (PRMT5)." (PMID 42150143, 2026). "As a result, such tumours show heightened dependence on residual PRMT5 activity and are particularly sensitive to PRMT5 inhibitors." (PMID 41537447, 2026). "We also discuss emerging approaches such as rational combination therapies and tumor-selective PRMT5 inhibitors as potential paths toward treatment for ATLL." (PMID 41600858, 2026). "The antitumor effects of PARP inhibitors alone or in combination with either the MTAP inhibitor MTDIA or the PRMT5 inhibitor EPZ015666 were evaluated in solid tumor models, including MTAP-deficient tumor models in vivo." (PMID 42122132, 2026). "MTAP‐deficient tumours cannot efficiently catabolise MTA, leading to intracellular MTA accumulation and partial inhibition of PRMT5." (PMID 41537447, 2026). "There is also evidence that protein arginine methyltransferase 5 (PRMT5) activates the PI3K/AKT signaling pathway to support tumor metastasis." (PMID 40438725, 2025). "PRT543, a potent orally available PRMT5 inhibitor, has demonstrated an early signal of anti-tumor activity in a subset of patients with several solid and hematological cancers, including ACC." (PMID 39794830, 2025). "The downstream effect of PRMT5 activation—symmetric dimethylation of histone H2A—was significantly elevated in both tumor types." (PMID 41301499, 2025). "Our previous studies indicated that PRMT5 knockdown increases the CD8+ T cells into the tumor tissue." (PMID 41463372, 2025). "For example, the combination of the PP2A protein phosphatase inhibitor LB100 with a PRMT5 inhibitor has been reported to significantly reduce tumor size and prolong survival in animal models compared with monotherapy using LB100." (PMID 40450009, 2025).
tumor (continued). "The interaction among T cells, the tumor microenvironment, and PRMT5 represents a complex research area that holds promise for therapeutic interventions aimed at enhancing anti-tumor immune responses." (PMID 41463372, 2025). "Once the subcutaneous tumor volume reached 200 mm3, a combination of the dose‐escalating PRMT5 inhibitors GSK3326595 and CPT‐11 was administered to determine the optimal therapeutic dose." (PMID 40344511, 2025). "Both ADC and SCC tumor samples displayed significantly increased PRMT5 protein expression compared to their corresponding controls, with fold changes of 1.54 (p = 0.02) and 1.88 (p = 0.042), respectively." (PMID 41301499, 2025). "These inhibitors demonstrate high specificity and selectivity by targeting the methyltransferase activity of PRMT5, effectively suppressing tumor cell proliferation and survival." (PMID 40450009, 2025). "While MTA-cooperative PRMT5 inhibitors are predicted to be the closest winner in the race, issues with MTA metabolism in the surrounding tumor microenvironment questions the actual applicability of an MTA-rich environment in PRMT5 inhibition." (PMID 41439984, 2025). "PRMT5 has been reported to be upregulated in several tumor types [Kim and Ronai, 2020; Sapir and colleagues, 2021]." (PMID 41150697, 2025). "Research on PRMT5 is relatively advanced, with studies indicating its significance as a crucial anti‐tumour molecule." (PMID 40078091, 2025). "In the context of CRC, the NO pathway metabolites are found to be altered, with enzymes such as ARG1, PRMT1, and PRMT5 being overexpressed in both tumor and tumor-adjacent tissues." (PMID 41268067, 2025). "Mice in the AMG193 and control groups showed poor tumor suppression, whereas those in the PRMT5 inhibitor group exhibited substantial tumor inhibition." (PMID 40450009, 2025). "Preclinical studies have shown that dual inhibition of PRMT1 and PRMT5 can produce synergistic tumor suppression, but the broader consequences of disrupting such interactions on normal tissue homeostasis require further investigation." (PMID 40791817, 2025). "PPM1B inhibits tumor cell colonization and metastasis by modulating MP and PRMT5; thus, the indirect tumor suppressor nature of MP was verified." (PMID 41301499, 2025). "A positive correlation between PRMT5 mRNA level and tumor grade was observed (TISIDB database, ρ = 0.254, p < 0.01)." (PMID 40384988, 2025). "These inhibitors competitively bind to the SAM-binding site of PRMT5, effectively inhibiting its methyltransferase activity, which, in turn, reduces tumor cell proliferation and survival." (PMID 40450009, 2025). "Results indicated that PRMT5 reduced tumor cell migration and increased the apoptosis of both U14 cells and Siha cells in vitro." (PMID 41463372, 2025). "Here, we demonstrate that BCSCs are more resistant to cisplatin and radiotherapy-induced cell death compared to the bulk tumour population, repair damaged DNA more efficiently than bulk cells, and that this is dependent on PRMT5 activity." (PMID 39695328, 2025). "Loss of PPM1B thus leads to sustained MYPT1 phosphorylation, reduced MP activity, and enhanced PRMT5 activation—a cascade that promotes tumorigenesis via epigenetic silencing of tumor suppressor genes." (PMID 41301499, 2025). "Consistent with in vitro results, in vivo tumor growth was significantly impaired in PRMT5 depletion group comparing with that in the scramble group." (PMID 40384988, 2025). "Immunofluorescent staining further confirmed the elevated phosphorylation at Thr80 of PRMT5 in tumor tissues." (PMID 41301499, 2025). "The results revealed that PRMT5 deficiency led to elevated expression levels of CXCL10, which plays a crucial role in attracting CD8+ T cells to the tumor site." (PMID 41463372, 2025). "In C57BL/6 mice, the percentage of CD4+ T and CD8+ T cells in the tumor microenvironment was significantly elevated in the PRMT5 knockdown group compared to the control group." (PMID 41463372, 2025).
tumor (continued). "The untreated PRMT5 KO tumors exhibited a 46% reduction in tumor volume compared to the untreated WT tumors (958.5 mm3 vs. 1765.5 mm3, p = 0.009)." (PMID 40723820, 2025). "We sought to determine the pathway by which PRMT5 restricts the activation and recruitment of immune cells, which defines tumor immune evasion, as well as the therapeutic effect of GSK3326595 in CRC." (PMID 39781264, 2025). "Combined PRMT5 inhibition with Pt resulted in synergistic cellular cytotoxicity in vitro and reduced tumor growth in vivo in Pt-resistant patient-derived xenograft tumors." (PMID 40091834, 2025). "In MTAP-deficient tumor cells, the accumulation of MTA within cells binds to PRMT5, forming the PRMT5/MTA complex." (PMID 39762212, 2025). "PRMT5 is known to aid tumor progression, yet its role and regulation in hypoxia remains underexplored." (PMID 41150697, 2025). "Our findings indicated that the knockdown of PRMT5 in the tumor microenvironment resulted in increased levels of IFN-γ and TNF-α expression in both CD4+ and CD8+ T cells." (PMID 41463372, 2025). "Protein arginine methyltransferase 5 (PRMT5) complexes with methylosome protein 50 (MEP50) play crucial roles in tumor progress." (PMID 41090362, 2025). "Despite its significance, the role of PRMT5 in T cell migration within the tumor milieu remains underexplored, particularly concerning strategies to modulate PRMT5 activity for enhancing the immune response against tumors." (PMID 41463372, 2025). "Future studies elucidating how PRMT5 directs specific splicing events in BCSCs has the potential to provide valuable biological insights into the survival mechanisms of this enduring tumour-initiating cell subpopulation." (PMID 39695328, 2025). "Currently, numerous small molecule inhibitors targeting PRMT5 have been developed, exhibiting anti-tumor effects in a variety of solid and hematological tumors, with some advancing to Phase I or Phase II clinical trials." (PMID 39885614, 2025). "Consistent with the previous work, TLR3 rescue contributed to a remarkable increase in liver metastasis in tumor-bearing mice, while either c-Myc inhibitor or PRMT5 inhibitor suppressed the metastasis induced by TLR3 rescue." (PMID 40675966, 2025). "Remarkably, our findings for the first time, comprehensively demonstrate the nuanced relationship between PRMT5-mediated histone methylation, DNA methylation and alternative splicing governing tumor progression under hypoxia." (PMID 41150697, 2025). "In a mouse model, circRHOT1 knockdown reduced tumor growth, decreased PRMT5 expression, and restored miR-204-5p levels." (PMID 41299506, 2025). "Histone H2A symmetric dimethylation as a functional readout showed a dramatic increase in tumor tissues and provides direct evidence of enhanced PRMT5 enzymatic activity in vivo." (PMID 41301499, 2025). "In soft tissue sarcomas, including OS, PRMT5 inhibition reduces glycolytic rates and slows tumor cell proliferation." (PMID 41268214, 2025). "Consistent with the results of PRMT5 depletion, PRMT5 inhibition significantly impeded tumor growth." (PMID 40384988, 2025). "In vivo, the combination of a PRMT5 inhibitor with anti-PD-1 therapy notably increased ferroptosis and reduced tumor growth." (PMID 40756764, 2025). "PRMT5 facilitates cell proliferation by repressing tumor suppressors and activating oncogenic networks." (PMID 41204384, 2025). "This study showed that GSK‐3326595, a phase II clinical drug targeting PRMT5, synergistically inhibited tumor growth when combined with chemotherapy in both subcutaneous tumor and AOM/DSS models in Balb/c mice." (PMID 40344511, 2025). "This study opens new avenues for understanding hypoxia-driven tumor progression through the interplay of PRMT5-mediated histone and DNA methylation, as well as alternative splicing." (PMID 41150697, 2025).
tumor (continued). "In contrast, a recent study reported that dependent on SIRT7-mediated PRMT5 K387 desuccinylation in tumors, PRMT5 contributes lipid metabolic reprogramming, tumor development, and metastasis, which is consistent with our study." (PMID 40777599, 2025). "Several PRMT5 inhibitors have demonstrated a notable antitumor effect in various tumor models, with key examples being GSK3326595 and JNJ-64619178." (PMID 40450009, 2025). "In line with the gene expression data, we found that PRMT5 protein levels were significantly higher and almost exclusively restricted to tumor cells compared with stromal cells." (PMID 40091834, 2025). "MRTX1719 selectively inhibits PRMT5 and PRMT5-promoted tumor activity, and is currently undergoing phase I/II clinical trials." (PMID 40790019, 2025). "In contrast, a significant reduction in tumor size was noted in the PRMT5 inhibitor group, and the combination treatment group exhibited stronger inhibitory effects." (PMID 40450009, 2025). "Secondly, it is plausible that PRMT5 can regulate the secretion of chemokines by tumor cells to recruit peripheral T cells into the tumor microenvironment, which requires further exploration." (PMID 41463372, 2025). "Among the genes with tumor driving properties, PRMT5 is the only target currently under the early phase clinical trial investigations in patients with ACC." (PMID 39794830, 2025). "Mechanistically, circRHOT1 acted as a sponge for the tumor-suppressive miR-204-5p, leading to its downregulation and subsequent upregulation of protein arginine methyltransferase 5 (PRMT5), a protein known to drive tumor growth and metastasis." (PMID 41299506, 2025). "Initially, chemotherapy was the main form of treatment; however, currently, PRMT5 inhibitors show a significant growth inhibition on tumor cells, specifically the synthetic fragment-based MRTX9768, which binds to the PRMT5-MAT complex." (PMID 40869229, 2025). "Knockdown of PRMT5 using siRNA enhanced the radiosensitivity of a panel of cell lines corresponding to tumor types typically treated with radiotherapy." (PMID 39068290, 2024). "MTA-cooperative PRMT5 inhibitors have the ability to maintain potent anti-tumor activities, but avoid dose-limiting hematology toxicity in cancer patients harboring homozygous loss of MTAP as shown by MRTX1719 and AMG193’s clinical studies." (PMID 39655075, 2024). "The use of PRMT5 inhibitors along with the chemotherapeutic agent gemcitabine has been shown to have a synergistic effect in tumor growth inhibition in PDAC cells through enhanced DNA damage." (PMID 38612768, 2024). "The dual role and localization of PRMT5 in BC further underscores its complex involvement in tumor biology." (PMID 39201539, 2024). "Exposure of the tumor cell lines to LLY-283 decreased PRMT5 activity and enhanced their radiosensitivity." (PMID 39068290, 2024). "Despite its pivotal role in tumor immunology, PRMT5 has been shown to be unable to modulate PD-L1 gene transcription through histone methylation (H3R2, H3R8, and H4R3) in cervical cancer cells." (PMID 39366935, 2024). "Several independent research efforts have uncovered that PRMT5 plays a pivotal role in the regulation of genes that either stimulate or suppress tumor growth." (PMID 38911125, 2024). "This new class of MTA‐cooperative PRMT5 inhibitors overcomes prior issues of drug toxicity and kills the tumor cells selectively, realizing a good application prospect." (PMID 39711357, 2024). "CMP5, the first PRMT5-specific inhibitor, was identified by screening the ChemBridge CNS-Set library of small molecules and shows reduced tumor cell viability by inhibiting PRMT5." (PMID 39201539, 2024). "Here, the systemic metabolic increase of the MTA:SAM ratio suppresses the catalytic activity of PRMT5 activity, which alters tumor cells more than normal cells to mimic the synthetic lethal phenotype." (PMID 38000655, 2024).
tumor (continued). "Collectively, these data indicate that PRMT5 enhances the expression of genes involved in tumor progression via HIF-1α pathway activation." (PMID 38666828, 2024). "Like the decreased number of sphere-forming cells, the growth of A549 cell tumours transplanted into nude mice was also reduced in PRMT5-inducible-knockdown cells." (PMID 38760429, 2024). "In the initial preclinical study of LLY-283 as a radiosensitizer described here, a single dose reduced tumor sDMA levels for at least 24 h, indicating the effective targeting of PRMT5 under in vivo conditions." (PMID 39068290, 2024). "Third, the Arg residue at position 110 can be methylated by protein arginine methyltransferase 5 (PRMT5) and this methylation impairs the Pdcd4’s tumor suppressor function." (PMID 39459035, 2024). "To investigate the potential of PRMT5 to serve as a target for radiosensitization, we used a panel of cell lines corresponding to tumor types typically treated with radiotherapy." (PMID 39068290, 2024). "As shown, LLY-283 treatment of the three tumor cell lines resulted in a dose dependent decrease in sDMA levels indicative of PRMT5 inhibition." (PMID 39068290, 2024). "To investigate the potential of PRMT5 as a clinically relevant target for tumor radiosensitization, we used the PRMT5 inhibitor LLY-28338." (PMID 39068290, 2024). "Because we examined the anti-tumour functions of PRMT5 inhibitors in primary ATL cells, the detailed mechanism and functions underlying PRMT5 inhibitors need to be investigated using in vivo experiments." (PMID 38474089, 2024). "Treatment of mice with LLY-283 decreased tumor PRMT5 activity and significantly enhanced the radiation-induced growth delay." (PMID 39068290, 2024). "SIRT7 catalyzes the desuccinylation of PRMT5, thereby augmenting its methyltransferase activity and inhibiting its ubiquitination, thereby promoting lipid metabolic reprogramming, tumor growth, and tumor metastasis in HCC." (PMID 39519130, 2024). "Comparison of sDMA levels in untreated cells showed that PRMT5 activity in the tumor cell lines was significantly higher than in the normal fibroblast cell line MRC9." (PMID 39068290, 2024). "In tumor xenograft-bearing mice, daily oral administration of MRTX1719 led to dose-dependent inhibition of PRMT5-dependent protein modification, correlated with anti-tumor activity." (PMID 39201539, 2024). "Specifically, circGSK3β positively regulates PRMT5 expression via miR-338-3p, thereby facilitating the recruitment of H3K4me3 to the PD-L1 promoter, ultimately fostering immune escape and tumor progression in BC." (PMID 39366935, 2024). "Transfection with siRNA to PRMT5 resulted in a significant enhancement of radiosensitivity in all three tumor cell lines U251, PSN1 and MDA-MB-231, with DEFs (Dose Enhancement Factor at a surviving fraction of 0.1) of 1.54, 1.41 and 1.53, respectively." (PMID 39068290, 2024). "Of note, near 95% tumor growth inhibition after 21 days of oral dosing of EPZ015666 was reported in multiple MCL xenograft models, thus highlighting the potent anti-tumor activity of this PRMT5 inhibitor." (PMID 39528914, 2024). "Treatment of the normal human fibroblast cell line MRC9 with LLY-283 reduced PRMT5 activity as reflected by sDMA levels to a similar degree as in the tumor cells." (PMID 39068290, 2024).